PDE6B (phosphodiesterase 6B)
Diseases named in the same sentence as PDE6B in open-access papers (continued):
Sharing a sentence is not in itself a finding about the gene and the disease.
tumor (5 papers, 2006 to 2025). "In the Pde6b mutant rd1 mouse, Olaparib significantly delayed photoreceptor loss and affected the release of extracellular vesicles associated with immune modulation, tumor invasion, regeneration, degenerative processes, cellular communication, cell homeostasis, and neovascularization." (PMID 34638907, 2021). "In contrast, PDE6B and PDE6C were significantly, and in many cases highly, expressed in all eight patients’ tumor tissues." (PMID 24683528, 2013). "These transcripts represent mRNAs that are expressed from 4-cell EGA though the preimplantation period and include CCBE1, a tumour suppressor gene with a suggested role in extracellular matrix remodelling and the cyclic AMP antagonist PDE6B responsible for removing cAMP." (PMID 23717564, 2013).
PDE6B also shares sentences with these, for which no sentence is quoted: infection (49 papers); tuberculosis (18); pulmonary TB (8); Granuloma (4); retinoschisis (3); Gliosis (2); hyperopia (2); immune deficiency (2); ischemia (2); lung disease (2); achromatopsia (1); age-related macular degeneration (1); ataxia telangiectasia (1); basal cell carcinoma (1); bladder cancer (1); Cerebral ischemia (1); choroideremia (1); combined immunodeficiency (1); deafness (1); depression (1); diabetic retinopathy (1); Epiretinal membrane (1); fragile X syndrome (1); glomerulonephritis (1); hearing loss (1); heart failure (1); Hypercholesterolemia (1); immunodeficiency (1); Insulin resistance (1); ischemic stroke (1).
A further 14 diseases each share a sentence with PDE6B in 1 paper.